CDC25A (cell division cycle 25A)
Diseases named in the same sentence as CDC25A in open-access papers (continued):
Sharing a sentence is not in itself a finding about the gene and the disease.
cervical cancer (continued). "Together, the results of our study demonstrate that Cdc25A protects cervical cancer cells against autophagy-mediated ferroptosis by upregulating ErbB2 levels through PKM2 dephosphorylation." (PMID 34743185, 2021). "In summary, we demonstrated that the Cdc25A/PKM2/ErbB2 axis is a crucial pathway in sorafenib-induced ferroptosis of cervical cancer cells." (PMID 34743185, 2021). "Cdc25A increased the resistance of cervical cancer to sorafenib, while knockdown of ErbB2 blocked these effects." (PMID 34743185, 2021). "In our study, in vitro results were reproduced in vivo, where downregulation of CDC25A reduced the growth rate of cervical cancer xenograft tumors in mice, which was partly in line with a previous study." (PMID 34266408, 2021). "Here, we report that CDC25A is highly expressed and miR‐122‐5p lowly expressed in cervical cancer tissues and cells." (PMID 31505105, 2019). "Collectively, these results suggest that CDC25A can reduce the sensitivity of cervical cancer cells." (PMID 31505105, 2019). "We found that the higher expression of CDC25A in cervical cancer tissues was related to more advanced clinical stage and earlier lymph node metastasis, but not to age, tumor volume and CA125 level." (PMID 31505105, 2019). "Subsequently, χ2 test and logistic regression analysis were used to analyze the relationship between the expression level of CDC25A and the clinicopathological indicators of patients with cervical cancer." (PMID 31505105, 2019). "In conclusion, our data suggest that miR‐122‐5p enhances the radiosensitivity of cervical cancer cells by targeting CDC25A." (PMID 31505105, 2019). "The results showed that the expression of CDC25A was significantly increased in six kinds of cervical cancer cells (HeLa, HeLa229, C‐33A, CaSki, ME180 and SiHa) compared with that of normal cervical epithelial cells." (PMID 31505105, 2019). "The aim of this study was to investigate the expression of miR‐122‐5p and CDC25A in cervical cancer cells and their role as regulatory mechanisms in the radiosensitivity of cervical cancer cells." (PMID 31505105, 2019). "This study confirmed that CDC25A can induce radiation resistance in cervical cancer cells, and that the expression of CDC25A is negatively regulated by miR‐122‐5p." (PMID 31505105, 2019). "miR‐122‐5p and CDC25A are expected to further elucidate the potential treatment for patients with cervical cancer and improve prognosis." (PMID 31505105, 2019). "Knockdown of CDC25A can increase the sensitivity of cervical cancer cells to radiotherapy, inhibit the survival of cervical cancer cell colonies and promote apoptosis." (PMID 31505105, 2019). "The expression of CDC25A in cervical cancer cells was detected by western blot at different radiation doses." (PMID 31505105, 2019). "Next, to study the regulation of CDC25A on the sensitivity of cervical cancer cells to radiotherapy, HeLa and SiHa cells were selected for further experiments." (PMID 31505105, 2019). "Furthermore, X-ray radiation has been demonstrated to increase CDC25A’s expression, increasing radiation resistance in cervical cancer cells." (PMID 36803831, 2023). "LINC00662 is reported to be connected with CDC25A in cervical cancer." (PMID 36685972, 2022). "Recently, it has been reported that Cdc25A is elevated in cervical cancer tissues and cells." (PMID 34743185, 2021). "Therefore, we concluded that Cdc25A suppressed cervical cancer cell ferroptosis by dephosphorylating PKM2 in the nucleus." (PMID 34743185, 2021). "We found that Cdc25A was decreased during sorafenib-induced ferroptosis in cervical cancer cells." (PMID 34743185, 2021). "Co-treatment with 3-MA or overexpression of Cdc25A upregulated p62 and FTH1 levels and downregulated the LC3-II/LC-I ratio and TfR1 level in sorafenib-treated cells, indicating that overexpression of Cdc25A suppressed sorafenib-induced autophagy in cervical cancer cells." (PMID 34743185, 2021).
cervical cancer (continued). "In addition, in cervical cancer, CDC25A has been reported to reduce cell apoptosis whereas increase cell viability following radio therapy." (PMID 34266408, 2021). "Also, CDC25A was identified as an important oncogene in cervical cancer during the transition between dysplasia and carcinoma." (PMID 34266408, 2021). "The function of CDC25A in cervical cancer growth in vivo was further explored." (PMID 34266408, 2021). "Furthermore, upregulation of Cdc25A increases the resistance of cancer cells to radiotherapy, while knockdown of Cdc25A promotes cervical cancer cell apoptosis." (PMID 34743185, 2021). "Moreover, the viability of Cdc25A/PKM2 S37D co-transfected cervical cancer cells was decreased to a similar extent as vector-transfected cells by sorafenib treatment." (PMID 34743185, 2021). "Therefore, we planned to validate the possible links between ALX3 and CDC25A and their functions in cervical cancer." (PMID 34266408, 2021). "CDC25A has also been reported to be necessary for cervical cancer cell progression." (PMID 34266408, 2021). "Furthermore, overexpression of Cdc25A enhanced the resistance of cervical cancer cells to sorafenib-induced ferroptosis, and the knockdown of ErbB2 blocked the effects of Cdc25A." (PMID 34743185, 2021). "Finally, we evaluated the function of Cdc25A in cervical carcinoma in vivo by using a nude mouse xenograft model." (PMID 34743185, 2021). "To investigate whether the radiotherapy resistance of cervical cancer cells is related to the expression level of CDC25A, we first detected by IHC the expression level of CDC25A in cancer tissues and adjacent tissues from 77 patients with cervical cancer." (PMID 31505105, 2019). "Notably, among the six types of cervical cancer cells, we found that the expression level of CDC25A in SiHa cells was the highest, whereas the expression level of HeLa cells was the lowest." (PMID 31505105, 2019). "Under X‐ray irradiation, up‐regulation of CDC25A can promote the radiation resistance of cervical cancer cells, whereas overexpression of miR‐122‐5p or knockdown of CDC25A inhibits the survival and induces apoptosis of cervical cancer colonies." (PMID 31505105, 2019). "Thus, we confirmed that miR‐122‐5p can inhibit the expression of CDC25A, thereby promoting the radiosensitivity of cervical cancer cells." (PMID 31505105, 2019). "The relationship between CDC25A expression and clinical pathological factors in cervical cancer." (PMID 31505105, 2019). "The expression of CDC25A in different cervical cancer cells was detected by western blot." (PMID 31505105, 2019). "We successfully constructed cell models with overexpressed CDC25A and lowly expressed CDC25A, and found that overexpression of CDC25A can significantly improve the resistance of cervical cancer cells to radiotherapy, promote the survival of cervical cancer cell colonies and inhibit apoptosis." (PMID 31505105, 2019). "Therefore, we concluded that Cdc25A was elevated in cervical cancer tissues." (PMID 34743185, 2021). "However, the regulatory networks involving CDC25A in cervical cancer development remain largely unknown." (PMID 34266408, 2021). "Interestingly, we found that Cdc25A could suppress sorafenib-induced ferroptosis in cervical cancer cells." (PMID 34743185, 2021). "Through bioinformatics analysis, we found that CDC25A is a potential target gene of miR‐122‐5p, which prompted us to investigate whether miR‐122‐5p can regulate the expression of CDC25A and its relationship with the radiotherapy resistance of cervical cancer cells." (PMID 31505105, 2019). "This study suggested that the ALX3 increased CDC25A expression through KDM2B-mediated demethylation of H3K4me3, which induced proliferation and cell cycle progression of cervical cancer cells." (PMID 34266408, 2021). "Altered expression of CDC25A and ALX3 was introduced in vitro and in vivo to access their functions in cervical cancer development." (PMID 34266408, 2021).
cervical cancer (continued). "Ferroptosis, which is regulated by the Cdc25A/PKM2/ErbB2 pathway, may serve as a therapeutic target in cervical cancer." (PMID 38722283, 2024). "Consistently, both the protein and mRNA levels of Cdc25A were significantly upregulated in cervical cancer tissues compared to non-tumour tissues." (PMID 34743185, 2021). "We implanted non-transfected or transfected human cervical cancer cells (vector, Cdc25A, Cdc25A + sh-NC, Cdc25A + sh-ErbB2) into nude mice, and 7 days later, saline or sorafenib was injected intraperitoneally every other day for 30 days." (PMID 34743185, 2021). "By analysing the TCGA dataset, we found that the level of Cdc25A in cervical cancer tissues was much higher than that in normal cervical tissues." (PMID 34743185, 2021). "Nevertheless, the exact role of Cdc25A in cervical cancer and the signalling pathways involved are not fully understood." (PMID 34743185, 2021). "Cell division cycle 25A (CDC25A) has been shown to induce radioresistance in a variety of tumor cells, but the role of CDC25A in the radioresistance of cervical cancer has not been fully elucidated." (PMID 31505105, 2019). "Furthermore, using IHC, we observed that the signal intensity of Cdc25A was much higher in cervical cancer tissues than in non-tumour cervical tissues." (PMID 34743185, 2021). "In this study, by analyzing the correlation between the expression levels of miR‐122‐5p and CDC25A in the cancer tissues of 77 patients with cervical cancer, we found a negative correlation between them, suggesting a potential regulatory relationship between them." (PMID 31505105, 2019). "However, the role of CDC25A in the radioresistance of cervical cancer and its mechanism has not been fully elucidated." (PMID 31505105, 2019).
melanoma (13 papers, 2011 to 2025). A malignant, usually aggressive tumor composed of atypical, neoplastic melanocytes. "Meanwhile, there are some limitations in our work, with further studies required to explore the underlying mechanisms of CDC25A in regulating melanoma progression in vitro and in vivo." (PMID 40216745, 2025). "Compound 7 arrested melanoma cells in G2/M, causing a reduction of the protein levels of CDC25A and, more consistently, of CDC25C." (PMID 26474275, 2015). "In conclusion, these results are consistent with a role of CDC25A inhibition in suppressing cell proliferation and disrupting the cell cycle in melanoma cells." (PMID 40216745, 2025). "The Q1 cohort demonstrated significantly elevated expression of CCNA2, CCNB1, CCND1, and CDH2, indicating CDC25A’s potential regulatory role in coordinating melanoma cell cycle progression with EMT dynamics." (PMID 40216745, 2025). "Functional investigation reveals that CDC25A inhibition suppresses the proliferation of melanoma cells and sensitizes melanoma cells to chemotherapy and NK cell therapy." (PMID 40216745, 2025). "Meanwhile, CCK-8 assays suggested that CDC25A inhibition enhance NK cell-mediated killing of melanoma cells." (PMID 40216745, 2025). "Our results indicated that CDC25 family members, particularly CDC25A, play a critical role in the malignant progression of melanoma." (PMID 40216745, 2025). "Based on CDC25A expression levels, melanoma patients were divided into quartiles (Q1–Q4), with Q1 denoting the highest-expressing 25% of samples and Q4 representing the lowest-expressing 25%." (PMID 40216745, 2025). "Together, these results indicate that CDC25A plays a role in the resistance of melanoma cells to NK cell-mediate killing." (PMID 40216745, 2025). "Our results demonstrated that melanoma cell was more sensitive to doxorubicin when CDC25A was lowly expressed." (PMID 40216745, 2025). "In melanoma, the expression of CDC25A was positively correlated with cell cycle, DNA damage, DNA repair, and proliferation scores, and negatively correlated with angiogenesis, differentiation, inflammation, and quiescence scores." (PMID 40216745, 2025). "Our results revealed that CDC25A inhibition suppressed cell proliferation and disrupted the cell cycle in melanoma cells." (PMID 40216745, 2025). "Specifically, the overexpression of either CDC25A and/or CDC25B has been observed in multiple tumor types, including melanoma, where it is frequently associated with a more aggressive and metastatic phenotype." (PMID 33003469, 2020). "CDK2 and CDK6, cyclins D1, E, and D3 and phosphatase CDC25A are consistently overexpressed in metastatic melanomas compared with nevus tissue." (PMID 26474275, 2015). "The overexpressed genes in the ulcerated melanoma cluster included many genes with reported functional roles in cell cycle regulation and proliferation, such as cell division cycle 25a (CDC25a) and MAPKK12." (PMID 23383013, 2013). "Furthermore, we focused on melanoma and systematically explored CDC25A expression and its clinical correlations." (PMID 40216745, 2025). "Also, inhibiting CDC25A suppressed the EMT process of melanoma cells as evidenced by increased expression of E-cadherin, as well as decreased N-cadherin and vimentin expression." (PMID 40216745, 2025). "In conclusion, our study suggests that CDC25 family may serve as a significant biomarker for diagnosis and prognosis across multiple cancers, with CDC25A as a promising therapeutic target for melanoma." (PMID 40216745, 2025). "Additionally, our findings indicate that CDC25A contributes to melanoma cells’ resistance to NK cell-mediated killing." (PMID 40216745, 2025). "Therefore, we explored the synergistic effects of CDC25A expression and infiltration of activated or resting NK cells on melanoma patient survival." (PMID 40216745, 2025). "High expression of CDC25A/C was a bad prognostic factor in melanoma." (PMID 40216745, 2025).
melanoma (continued). "In conclusion, these results suggest that CDC25A inhibition could increase the sensitivity of melanoma to doxorubicin." (PMID 40216745, 2025). "Additionally, we confirmed that CDC25A inhibition enhanced the sensitivity of melanoma cells to chemotherapy and NK cell therapy." (PMID 40216745, 2025). "We also confirmed that CDC25A inhibition could increase the sensitivity of melanoma to doxorubicin in vitro, suggesting that CDC25A may be a potential synthetic target for doxorubicin treatment in melanoma." (PMID 40216745, 2025). "We found that CDC25A inhibition could suppress the proliferation of melanoma cells and sensitize melanoma cells to doxorubicin and natural killer (NK) cell therapy." (PMID 40216745, 2025). "Moreover, cantharidin (CTD), another natural compound that shares many characteristics with TPL, shows a similar ability to inhibit cyclin A and CDC25A in the A375.S2 melanoma cell line." (PMID 33003469, 2020). "Consequently, the downregulation of PCNA protein and the CDC25A/CyclinB1/CDK1 pathway may be the mechanism of ZBSO against melanoma." (PMID 37081962, 2023). "Analysis of the TCGA-SKCM and GTEx datasets revealed elevated expression of NF2, SUZ39H1, CDC25A, GLRX5, and CISD3 in melanoma tissues, in contrast with the reduced expression of VDR, PPARD, CAMKK2, NT5DC2, and CHP1A." (PMID 40860143, 2025). "To confirm the function of CDC25A, we inhibited its activity using the NSC663284 inhibitor in two melanoma cell lines." (PMID 40216745, 2025). "These authors suggested that proteasome-mediated degradation of Cdc25A was responsible for the reduced activity of CDK2, resulting in the G1 arrest of the melanoma cells." (PMID 33228205, 2020). "Further studies presented that ZBSO could constrain CDC25A/CyclinB1/CDK1 signaling pathway in vitro and in vivo models of melanoma." (PMID 37081962, 2023). "Receiver operating characteristic (ROC) curves showed an area under the curve (AUC) >90.0% for KPNA2, DTL, BACE2, DTYMK, E2F3 and SLC25A13, >80.0% for CCNA2, FOXM1, KIF4A, SLC45A2, COPS8, SLC45A13 and 70.0% for CDC25A and LINC00520; all significantly discriminating melanoma from benign nevi." (PMID 36320118, 2022). "We identified the G1/S transition regulatory network with key pro-S phase genes (E2F, CCNE, CDK2, Cdc25A) induced in HBECs, but repressed or not regulated in melanoma cells." (PMID 22140489, 2011). "Taken together, our studies demonstrate that, within the CDC25 family, CDC25A, rather than CDC25B or CDC25C, plays a more dominant role in melanoma progression." (PMID 40216745, 2025). "As a result, high expression of CDC25A/C, but not CDC25B, predicted short survival of melanoma patients in OS, DSS, or PFS." (PMID 40216745, 2025). "Further analysis showed that CDC25A, not CDC25B or CDC25C, plays a more dominant role in melanoma development." (PMID 40216745, 2025).